FAM43B (family with sequence similarity 43 member B)
Synonyms: FLJ44952
Tractability: PROTAC: ubiquitination databases record sites on it.
Gene: Protein-coding gene on chromosome 1 (20,552,573 to 20,555,020, forward strand). Ensembl gene ENSG00000183114.
Subcellular location (Human Protein Atlas): Cytosol
Genetic constraint (gnomAD): Loss-of-function variants: 17 observed, 12.85 expected, observed/expected ratio (o/e) 1.32, 90% interval 0.9 to 1.85. The synonymous counts are far from expectation, so gnomAD's model fits this gene poorly and the ratio says little. Missense variants: 512 observed, 382.45 expected, observed/expected ratio (o/e) 1.34, 90% interval 1.24 to 1.44. Synonymous variants: 208 observed, 166.58 expected, observed/expected ratio (o/e) 1.25, 90% interval 1.11 to 1.4.
Homologues: Orthologues: chimpanzee FAM43B (100% identical), macaque FAM43B (98% identical), dog FAM43B (96% identical), rat Fam43b (94% identical), mouse Fam43b (93% identical), pig FAM43B (93% identical), zebrafish fam43b (51% identical), tropical clawed frog fam43b (45% identical), Drosophila melanogaster CG8312 (27% identical), Caenorhabditis elegans F52D10.2 (22% identical), Drosophila melanogaster CG42673 (16% identical), Caenorhabditis elegans dyc-1 (13% identical), and 6 more. Paralogues in human: FAM43A (45% identical), LDLRAP1 (16% identical), NOS1AP (15% identical), NUMBL (15% identical), NUMB (14% identical), DAB2 (13% identical), DAB1 (13% identical), MAPK8IP1 (12% identical), MAPK8IP2 (12% identical), GULP1 (3% identical), C1orf226 (2% identical).
Diseases named in the same sentence as FAM43B in open-access papers:
FAM43B is named in the same sentence as 4 diseases in open-access papers, as found by Europe PMC text mining. Sharing a sentence is not in itself a finding about the gene and the disease.
FAM43B shares sentences with these, for which no sentence is quoted: non-small cell lung carcinoma (2 papers); hepatocellular carcinoma (1); multiple myeloma (1); periodontitis (1).